CD4 (CD4 molecule)
Diseases named in the same sentence as CD4 in open-access papers (continued):
Sharing a sentence is not in itself a finding about the gene and the disease.
colitis (continued). "To further determine which TH17 cytokines are responsible for inhibiting chemokine expression and protect the Tak1ΔM/ΔM mice against colitis and CRC, we performed intracellular staining of key TH17 cytokines (IL-17A, IL-17F, IL-21, and IL-22) in CD4+ cells from intestinal LP." (PMID 40749055, 2025). "Ameliorated colitis through AhR signaling activation, increased the expression of anti-inflammatory cytokines, and resulted in the expansion of IL-10-producing CD4+ T cells and IL-22-producing CD3−RORγt+ cells, but not CD4+Foxp3+ regulatory T cells." (PMID 40756994, 2025). "To address this issue, we examined immune cell populations in colitis-sensitive and colitis-resistant mouse models by immunohistochemistry (IHC) staining of myeloperoxidase (MPO; for neutrophils), CD68 (for macrophages/monocytes), CD4, and CD8 on colon sections from different mouse strains." (PMID 40749055, 2025). "However, in the lungs of DSS-induced colitis mice both α4β7+ and CCR9 + CD4 + cells were significantly upregulated in the lung tissues (31.5% vs 1.4%; P < 0.001)." (PMID 40435188, 2025). "Colitis was induced in Rag2−/− mice by intravenously injecting CD45.1+ naïve CD4+ T cells with or without cotransferring CD45.2+ Treg cells from WT or Prdm1-CKO mice." (PMID 40680114, 2025). "Patients with ICI colitis who underwent combined anti-CTLA4 and anti-PD1 therapy exhibited an enrichment of bone marrow-derived cells, notably inflammatory DCs, alongside a reduction in CD4+ tissue-resident memory T cells." (PMID 39456702, 2024). "In our previous study, we found that CD4+ Treg-of-B cells can alleviate the intestinal inflammation and suppress Th1 and Th17 cytokines IFN-γ, TNF-α, and IL-17 in CD4+CD45RBhi T cell-induced colitis through an IL-10-independent mechanism." (PMID 39085655, 2024). "In PPs, the colitis group that received the probiotic mixture showed significantly upregulated CD4+ T cell frequencies compared to the colitis group that did not receive the probiotic mixture (p < 0.01)." (PMID 39201260, 2024). "To rule out a role for mutant Tregs in the development of the disease, we injected either WT or KO Tregs into Rag1–/– mice and found that neither group of Tregs induced significant colitis like CD4+ T cell injection did." (PMID 39480507, 2024). "In the present study, we also found that the colitis mice presented similar results with lower frequencies of mTreg (CD4+Foxp3+, CD4+CCR7+Foxp3+, CD4+CCR7−Foxp3+) cells and higher mTh17 (CD4+CCR6+, CD4+CCR7+CCR6+, CD4+CCR7−CCR6+) cells." (PMID 38202824, 2024). "Specifically, introducing WT CD4+ CD45RBhigh T cells into RAG KO mice triggers persistent inflammation in both the small and large intestine, while transferring the same T cells into TCR KO mice elicits only mild duodenitis and colitis." (PMID 38543070, 2024). "Because it is well known that CD45RBhi but not CD45RBlo CD4+ T cells can induce severe colitis in lymphodeficient mice, we first analyzed the composition of these two CD4+ T lymphocyte populations." (PMID 39630890, 2024). "OMVs secreted by Bacteroides fragilis carries polysaccharide A (PSA), which is delivered to intestinal dendritic cells and induces CD4 regulatory T cells (Tregs) to produce IL-10, which down-regulates the inflammatory response and effectively ameliorates DSS-induced colitis." (PMID 39628464, 2024). "In a separate internal study, circulating CD4+ monocytes also increased in dogs that were undergoing acute gastrointestinal distress (pancreatitis or colitis) at the time of blood draw (data not shown)." (PMID 39911485, 2024). "In addition, FexD largely blocked the colitis-induced increases of IL17A+ and IFN-γ+ in CD4+ T cells and IFN-γ+ in CD8+ T cells in both ileal and colonic lamina propria." (PMID 38258906, 2024).
colitis (continued). "Here, in an effort to further explore the role of 5-HT7 in the pathogenesis of colitis, we conducted a series of studies investigating the impact of the novel 5-HT7 receptor antagonists, MC-170073 and MC-230078, in both the DSS and CD4+ T-cell transfer models of colitis." (PMID 38713616, 2024). "Weekly injections of anti-CD4 mAb (clone GK1.5) or isotype control mAb began at 4 wk of age, prior to colitis development (typically 10–12 wk), and lasted until 20 wk of age where colitis is typically overt in P440S mice." (PMID 37962568, 2024). "Unlike macrophage, specific deletion of IL-10 in CD4+ T cells (∼80% are Tregs) leads to the development of spontaneous colitis in mice, similar to the phenotype of complete IL10−/− mice." (PMID 38502145, 2024). "Accordingly, after imprinting gut tropism in CD4+ T-cells, they were treated with the experimental peptides (TM6C, TM7C, or vehicle) and then i.v. transferred into Drd5−/− recipient mice undergoing DSS-induced colitis." (PMID 39337509, 2024). "We identified polyfunctional mucosal CD4+ and CD8+ T cells that co-produce IFNγ, other pro-inflammatory cytokines (e.g. IL22, IL17A) and cytotoxic molecules, including granzyme B, as key effector cells in CPI colitis." (PMID 37872166, 2023). "Moreover, KCa3.1 channel blocker TRAM-34 reduces the severity of DSS-induced colitis and normalizes the expression of KCa3.1, NDPK-B, and Th1 cytokines in the mesenteric lymph node CD4+ T cells." (PMID 36459135, 2023). "The regulation of the immune response in the gut-draining lymph nodes was also affected by the MLT treatment of colitis, with an important increase in the frequency of regulatory T cells, despite a reduced CD3+CD4+ population producing the suppressor cytokine IL-10." (PMID 36838425, 2023). "As well as being expanded in CPI colitis, Ifng-expressing lymphocytes co-expressed Gzmb, and this was found to be most highly co-expressed and correlated within the cycling CD8 T cells, TH1/TH17 and cycling CD4+ T cells clusters." (PMID 37872166, 2023). "Summing up, tofacitinib is effective in the treatment of experimental CD4+ T cell transfer colitis in mice while it does not prevent occurrence of colitis." (PMID 36882462, 2023). "In dextran sulfate sodium (DSS)-induced colitis, splenic NKG2D+CD4+ T cells could be divided into two subpopulations based on the expression of NK1.1, namely TGF-β+FasL+T-bet+NK1.1− cells and IFN-γ+IL-17+IL21+granzymeB+perforin+T-bet−RORγt+NK1.1+ cells." (PMID 38139373, 2023). "No significant colitis was observed in TslprKO and WT mice that were sublethally irradiated without a CD4+ T cell transfer." (PMID 37427591, 2023). "Surprisingly, incoming CD4+ T cells induced lethal colitis in adult Rag1-knockout animals that lacked the TSLP receptor (Rag1KOTslprKO)." (PMID 37427591, 2023). "Here, we show that IL23 blockade, or genetic ablation, reduced pathogenic cytokine production by CD4+ T cells, but not CD8+ T cells in CPI colitis, and significantly attenuated disease development." (PMID 37872166, 2023). "Constitutive activation of mTORC1 by CD4+ specific deletion of TSC1 promotes Th1 and Th17 cell differentiation and suppresses immunosuppressive activity of Treg, resulting in an enhanced disease severity in an adoptive T cell transfer colitis model." (PMID 37809060, 2023). "Studies have shown that transferring the two Treg cells CD4+ and CD25+ into colitis-affected mice can lessen the infiltration of inflammatory cells in the lamina propria and return the intestinal wall to its normal state, reversing the inflammatory response and healing the colitis." (PMID 37109555, 2023). "Supporting the importance of Th1 differentiation in IBD, a lack of IFN-γ in CD4 T-cells prevents the development of dextran sulfate sodium (DSS)-induced colitis in mice." (PMID 36769019, 2023).
colitis (continued). "In CPI colitis, Ifng-expressing CD8+ T cells upregulated a similar pattern of transcripts among the most highly upregulated 20 transcripts (albeit with a more limited repertoire of cytokines than CD4+ T cells)." (PMID 37872166, 2023). "Similarly, butyrate at high concentrations is shown to be pro-inflammatory during acute colitis in mice by stimulating expression of T-bet and IFN-γ in CD4 + T cells, while at low concentrations and steady state it promotes Treg differentiation." (PMID 37720032, 2023). "Glut1-depleted CD4+ T cells fail to trigger intestinal inflammation in nonsteroidal anti-inflammatory drug-induced T cell transfer colitis model in mice." (PMID 37809060, 2023). "Previous reports found that during DSS induced colitis, mice with a mutation to constitutively activate TRPV1 showed a significant increase in CD4+ T cells producing IL-17A but not IFNγ." (PMID 38109366, 2023). "In the context of a colitis-permissive intestinal microbiota, combination of immune checkpoint blockade with anti-CTLA4 and anti-PD-1 results in the emergence of IL23-dependent, polyfunctional, cytolytic, CD4+ and CD8+ T-cell responses that are functionally important in CPI colitis development." (PMID 37872166, 2023). "Furthermore, treatment with the pharmacological PDK4 inhibitor, GM-10395, compromises CD4+ T cell activation and attenuates DSS-induced colitis." (PMID 37809060, 2023). "Since T cells are not the main point of this project, the adoptive CD4+CD45RBhi T Cell transfer mouse colitis model was not involved." (PMID 36922750, 2023). "IFN-γ–deficient Th17 cells maintained their Th17 phenotype but failed to induce colitis in mouse models, and IL-17A+IFN-γ+CD4+ T cells were considered to be more pathogenic." (PMID 35784693, 2022). "In this study, CD4+CCR7+/− cells in mice with DSS-induced colitis were overactivated, and their subsets CD4+CCR7+IL-17A+ and CD4+CCR7−IL-17A+ increased significantly, while CD4+CCR7+IL-10+, CD4+CCR7−IL-10+, CD4+CCR7+Foxp3+, and CD4+CCR7−Foxp3+ decreased significantly." (PMID 35832382, 2022). "Nevertheless, the potential function of GPR65 in regulating mucosal CD4+ T cell functions during colitis and maintaining intestinal homeostasis remains not fully understood." (PMID 35343079, 2022). "Moreover, CD4-CTL were reported to be enriched in the mouse intestinal mucosa, as compared to secondary lymphoid organs, and to promote experimental colitis." (PMID 36479125, 2022). "They further determined that cure of colitis was IL-10 dependent, and that IL-10 producing CD4+CD25+ Tregs were mainly located in the lamina propria of the intestine suggesting functional compartmentalization of CD4+CD25+ T cells during disease states." (PMID 36466912, 2022). "Observation from the earlier study prompted increased CD4+ cell population, and IL22 cytokine expression in colitis patients was tightly correlated with upregulation of carbohydrate and nucleotide metabolism and downregulation of amino acid and lipid metabolism." (PMID 35263357, 2022). "Finally, B. fragilis can both prevent and cure colitis in mouse models by releasing PSA in outer membrane vesicles, stimulating plasmacytoid dendritic cells to act in concert with CD4+ T cells and conferring immunoprotection." (PMID 36071979, 2022). "Although DSS-induced colitis led to the expansion of CD4+ T cells, B cells, and macrophages, DKT did not influence these populations." (PMID 35720414, 2022). "The numbers of CD69−CD103− T cells and CD69+CD103+ CD4+ TRM cells expressing IFNγ or IL-17A were similar between mice with or without colitis." (PMID 35844584, 2022). "We further verified that demethylated Zbtb7b activated the maturation of CD4+T cells and repressed the differentiation of DP CD4+CD8+ T cells, resulting in the production of inflammatory cytokines and colonic inflammation in the UC and DSS-induced colitis model." (PMID 35761286, 2022).
colitis (continued). "The absence of GPR4 ameliorates colitis with lower histology scores, reduced CD4+ T helper cell infiltration, and decreased IFN-γ, iNOS, CXCL1, and CXCL2 expression." (PMID 35165253, 2022). "Since Th1/Th17 subsets are involved in exacerbating the inflammatory response in a DSS-induced colitis model, we assessed whether CeNP-PEG could affect the differentiation of helper CD4+ T cells." (PMID 35246140, 2022). "Majority of the CD69+CD103+ CD4+ TRM cells were Foxp3+ Treg cells that more than 70% of Foxp3+ Treg cells were CD69+CD103+ CD4+ TRM cells both in mice with or without colitis." (PMID 35844584, 2022). "Therefore, we considered that the over-expression of Zbtb7b promoted the differentiation of CD4+T cells, subsequently contributing to the production of inflammatory cytokines in the DSS-induced colitis model." (PMID 35761286, 2022). "Taken together, the expression of this G-protein coupled receptor by CD4+ T lymphocytes did not play an essential role in pathogenesis in the adoptive transfer model of colitis." (PMID 36389671, 2022). "This increased cytokine production by Arl4d−/− CD4 T cells, however, does not exacerbate CD4 T-cell-driven colitis but rather protects from extensive tissue inflammation and cell infiltration." (PMID 36078047, 2022). "Surprisingly, further analysis of CD4 subsets in a colitis disease model and BM chimera demonstrated a Th1-skewed effector CD4 T cell compartment, but there was no increase in Th17 cells." (PMID 36136607, 2022). "Furthermore, synthetic, disulfide-rich peptides based on ES products of A. caninum and N. americanus, reduced colitis symptoms in a TNBS model and suppressed CD4 + T cell proliferation and inhibited IL-2 and TNF production." (PMID 36186812, 2022). "When Zbtb7b is absent, the activated CD4+ IELs lose their inflammatory function, resulting in the inability to induce colitis." (PMID 35761286, 2022). "Alternatively, another report demonstrated with CD4+ T cell depletion that T cells of CD4+ but not CD8+ phenotype are responsible for the modulation of DSS-induced colitis." (PMID 34983695, 2022). "LysoPS-induced aggravation of colitis was impaired in mice lacking P2ry10 and P2ry10b, and their CD4+ T cells were hyporesponsive to LysoPS." (PMID 35608941, 2022). "In addition, HD-DCs were found to modify the anti-colitic CD4(+) T cells with the help of IL-10, and transfer of HD-DCs suppressed DNBS-induced colitis through activation of recipient IL-4 receptor-α." (PMID 36558772, 2022). "On the other hand, a subset of ICOS+ proliferative CD4+ T cells expanded significantly in both those who developed colitis and those who did not." (PMID 36173679, 2022). "Furthermore, we validated that Zbtb7b activated CD4+T cells and repressed CD4+ CD8+T cells in the inflamed colonic tissues of UC, which contributed to the colonic inflammation in the dextran sodium sulfate (DSS)-induced colitis model." (PMID 35761286, 2022). "Therefore, it is plausible that SB3 treatment suppresses mechanisms involved in CD4+ and CD8+ T cell chemotaxis and cytolytic activities, which are yet to be explored during colitis." (PMID 35887133, 2022). "Of note, the T cell response to the colitis process was totally blunted in the treated group, an effect evidenced across different T cell subpopulations, such as cytotoxic CD8+ T cells, Th1 (CD4+IFNg+), Th2 (CD4+IL4+), Th17 (CD4+IL17+), and Tregs (CD4+FoxP3+)." (PMID 34072532, 2021). "When CD4+CD25+ Treg cells are isolated from conventionally housed mice or GF mice and co-injected with naïve T cells in the adoptive T cell transfer model of colitis, recipients of GF Treg cells exhibit increased inflammation." (PMID 34421921, 2021). "Indeed, an initial short treatment of experimental IBD with analogue 5 increased the number of MLN Foxp3 + CD4 + CD25 + Treg cells and the gene expression of colonic FoxP3, as well as inducing tolerance to colitis recurrence." (PMID 33767180, 2021).
colitis (continued). "WT B. fragilis but not the ΔPSA mutant induces anti-inflammatory CD4+ CD45Rblow T cell population and protects animals from the T cell transfer model of experimental colitis." (PMID 34025663, 2021). "Moreover, recent research illustrated distinct immunological features of colonoscopy from CIC and IBD patients, with predominantly CD4+ T cells and Treg cells in the anti-CTLA-4-induced colitis and IBD patients, respectively." (PMID 34992611, 2021). "Similarly, CD4+ CAR-Tregs recognizing 2,4,6 Trinitrophenol (TNP) suppressed TNP-induced colitis in mice, decreased colonoscopy colitis scores, and increased survival." (PMID 33854514, 2021). "Using a translational humanized mouse model, LD IL-2 expands human Treg cells and is protective against TNBS-induced colitis that is independent of CD4+ HLA restriction." (PMID 34421921, 2021). "ET failed to alleviate colitis when OVA TCR enriched T cells were derived from IL-10−/− or CD4-dnTGFBRII mice." (PMID 33717186, 2021). "Although all mice receiving TNBS developed colitis, those receiving LD IL-2 exhibited reduced inflammation and injury compared to PBS (P < 0.001) that was similar to what we previously observed when CD4+ T cells were HLA restricted." (PMID 33717161, 2021). "T cells from patients with PD-1 colitis are predominantly in the CD8+ TRM cell populations (clusters 1 and 6) and are distinct from T cells from active UC, which are predominantly in the conventional and CD4+ T cell zones." (PMID 34147519, 2021). "A CD4-Cre loxP-flanked-METTL3 (METTL3fl/fl) mouse model exhibited more circulating naive T lymphocytes and less abundant activated CD4+ T cells, thus exerting a preventive role in the evolving colitis." (PMID 35127705, 2021). "Depletion of CD4+ T cells did not reduce intestinal inflammation, demonstrating that CD4+ T cells are dispensable for colitis development in this model." (PMID 34938670, 2021). "Using adoptive transfer studies in RAG2 KO recipient animals, we confirmed that CD8+ T cells rather than CD4+ T cells are the relevant colitis effector cells in Yeti mice." (PMID 33513946, 2021). "In contrast, the T‐cell transfer model of colitis assesses chronic colonic inflammation that arises after priming of microbiota‐specific naïve CD4+ T cells in the absence of a Treg cell compartment." (PMID 32966619, 2021). "In dextran sulphate sodium‐mediated colitis, the lack of Itgb8+ Tregs also exacerbates pathology, including the elevation of CD4+ T cells without altering Treg migration, activation or stability." (PMID 32463116, 2020). "The Rag2−/− mouse model of T-cell-mediated colitis also revealed a nonredundant role of BTK in CD4+ T-cell responses." (PMID 31431692, 2020). "Importantly, in vivo treatment with FANA-CD39-AS oligonucleotides results in a more favorable course of TNBS colitis induced in immunodeficient NOD/scid/gamma mice, previously re-populated using human CD4 cells with CD39-AS RNA expression." (PMID 33208731, 2020). "CD4 and CD8 T cells play a differential role in colitis and the antitumor response." (PMID 33127658, 2020). "A full length anti-CD4 antibody labeled with 111In was used for SPECT imaging in mice orally pre-treated with dextran sulfate sodium (DSS) which activates CD4+ T cells in the periphery and drives their influx into the colon, inducing colitis." (PMID 32582173, 2020). "As a result, we subsequently analyzed the cellular composition of the colon environment (including CD103+CD11b+ DC, CD3− NK1.1+ NK, CD4+, and CD8+ T cells) and found the significant infiltration of CD4+ and CD8+ T cells and the migration of DC cells into the colon LP of colitis mice." (PMID 32855978, 2020). "In keeping with murine colitis studies showing that IL-23 promotes inflammation through induction IFN-γ expression in Th17 cells, these MDR+ IL-17+IFN-γ+CD4+ T-cells (CCR6+CXCR3hiCCR4loCCR10negCD161+) cells had an inflammatory profile and in addition displayed resistance to glucocorticoids in vitro." (PMID 31906479, 2020).